FZD7 (frizzled class receptor 7)
Diseases named in the same sentence as FZD7 in open-access papers (continued):
Sharing a sentence is not in itself a finding about the gene and the disease.
melanoma (15 papers, 2008 to 2025). A malignant, usually aggressive tumor composed of atypical, neoplastic melanocytes. "High level of Wnt receptor, FZD7 is associated with enhanced metastatic potential of melanoma cells." (PMID 28137308, 2017). "Knocking down of FZD7 in a panel of four melanoma cell lines led to a significant reduction in lung metastases in animal models, arguing that FZD7 plays a causal role during metastasis formation." (PMID 26808375, 2016). "The WM266-4 cells expressed higher levels of FZD7 mRNA than WM115 cells (left) and had a higher tumor initiating frequency (right), further supporting the association among FZD7 expression, tumor initiation, and melanoma metastasis in patients." (PMID 26808375, 2016). "Despite these differences, the causal roles of FZD7 on tumor initiation, as reported here, indicate that the tumor initiating properties of melanoma cells are subject to similar regulations that impose on stem cells from other cancer types." (PMID 26808375, 2016). "We then investigated whether FZD7 plays a causal role in melanoma metastasis, using the experimental metastasis model." (PMID 26808375, 2016). "Early studies have also explored the significant activation of the WNT pathway through the action of FZD7 in BRAF inhibitor-resistant melanoma cells." (PMID 40611274, 2025). "Knockdown of FZD7 in melanoma cells inhibits the formation of xenograft tumors and metastatic growth in the lung following intravenous injection." (PMID 36620565, 2022). "In melanoma, glioblastoma, and osteosarcoma, FZD7 expression is increased and inhibition of FZD7 suppresses EMT." (PMID 34604862, 2021). "Using an experimental metastasis model, we discovered that high levels of the WNT receptor, FZD7, correlated with enhanced metastatic potentials of melanoma cell lines." (PMID 26808375, 2016). "A significant reduction in lung metastases was observed in all the knockdown cell lines, demonstrating that FZD7 is required for metastasis formation in melanomas." (PMID 26808375, 2016). "Consistent with its function in tumor initiation, knocking down FZD7 led to an inhibition of growth initiation of metastatic melanoma cells after seeding in lung." (PMID 26808375, 2016). "FZD7 is upregulated in human, metastatic melanoma cells, and shRNA mediated knockdown of FZD7 in these cells was able to inhibit formation of xenograft tumours and also metastasis following intravenous injection." (PMID 27196929, 2016). "We report here that a WNT receptor, FZD7, is required for both tumor initiation of melanoma cells and their metastatic growth in lung." (PMID 26808375, 2016). "Our data show that knocking down of FZD7 led to a decrease in metastasis size at this stage, consistent with its function on tumor initiation of melanoma cells." (PMID 26808375, 2016). "It significantly impeded metastasis formation from these cells, supporting the essential role of JNK on FZD7-mediated metastatic growth of melanoma." (PMID 26808375, 2016). "By week 2, however, a reduction in pHH3+ metastases was observed in the knockdown group, suggesting that FZD7 is required for the proliferation of melanoma cells in lung." (PMID 26808375, 2016). "Limited studies in melanoma also indicate a similar pro-oncogenic role of FZD7." (PMID 36620565, 2022). "FZD7 knock-down reduces tumor growth after subcutaneous injection of the WM1361 melanoma cell line as well as metastasis formation after tail-vein injection of several melanoma cells in NSG mice." (PMID 35158973, 2022). "Melanoma’s which develop resistance to treatment with BRAF inhibitor PLX4720 display upregulated Wnt5a which was consequently show to promote tumour growth via FZD7 and AKT." (PMID 27196929, 2016). "WNT3 and WNT5A were detected at a much higher level than WNT8 and WNT11, so we investigated further whether WNT3 and WNT5A signal through FZD7 in melanoma cells." (PMID 26808375, 2016).
melanoma (continued). "We report here that FZD7 is required for tumor initiation from melanoma cell lines, revealing for the first time a signaling pathway that regulates the cancer stem cell property in melanoma." (PMID 26808375, 2016). "Because of the known function of WNT signaling and FZD7 in stem cell maintenance and differentiation, we investigated whether FZD7 plays roles in melanoma stem cells." (PMID 26808375, 2016). "The shared FZD7-dependence among metastases from BI-sensitive and–resistant melanoma cells strongly indicate that these functions of FZD7 may be clinically relevant and targeted for melanoma treatment." (PMID 26808375, 2016). "To analyze whether WNT5A activates FZD7 in melanoma cells, we treated MA-2(shGFP) and MA-2(shFZD7) cells, or MeWo(shGFP) and MeWo(shFZD7) cells with recombinant WNT5A." (PMID 26808375, 2016). "FZD7 activated JNK in melanoma cell lines in vitro and the expression of a dominant negative JNK suppressed metastasis formation in vivo, suggesting that FZD7 may promote metastatic growth of melanoma cells via activation of JNK." (PMID 26808375, 2016). "We then investigated whether the effects of FZD7 on tumor initiation contribute to its function on metastasis initiation in melanoma, using the experimental metastasis model." (PMID 26808375, 2016). "Since high levels of FZD7 expression correlate with metastatic potential of melanoma cell lines, we asked whether this correlation is linked to its function on tumor initiation." (PMID 26808375, 2016). "FZD7 is a WNT receptor and is capable of signaling through either canonical or non-canonical WNT signaling pathways, both of which have been implicated in melanoma progression." (PMID 26808375, 2016). "In addition, it has been reported that FZD7 is a target of miR-485-5p in melanoma cells." (PMID 30154476, 2018). "In vitro activation of JNK by FZD7 suggests that FZD7 might promote melanoma metastasis via JNK." (PMID 26808375, 2016). "Although known at a descriptive level, FZD3, FZD7, and the most recent addition of FZD6 are involved in melanoma cell survival and invasion." (PMID 36620565, 2022). "In particular, WNT11-cognate receptor FZD7 and its co-receptor RYK were both consistently upregulated in metastatic melanomas in most of the studies." (PMID 33082334, 2020). "It significantly reduced the transcript levels of LEF1, WNT10B, MITF-M, c-MYC and CCND1 and increased the mRNA levels of FZD7 and DKK1 in all melanoma cell populations." (PMID 27351373, 2016). "OMP-18R5, a monoclonal antibody targeting several FZD including FZD7, is able to block tumor growth in xenograft mouse models for multiple cancers, but was not evaluated for melanoma." (PMID 35158973, 2022). "Knocking down of FZD7 suppressed JNK activation and metastatic growth in melanoma." (PMID 28137308, 2017). "Our data suggest that FZD7 activates JNK through non-canonical signaling to support metastatic growth in melanoma." (PMID 26808375, 2016). "FZD7-knockdown led to attenuated phosphorylation of JNK in both knockdown cell lines, suggesting that FZD7 trasmits non-canonical WNT signaling from WNT5A in melanoma cells." (PMID 26808375, 2016). "Finally, FZD7 activates JNK in melanoma cells in vitro, and the expression of a dominant negative JNK inhibited their metastasis formation in vivo, suggesting that FZD7 promotes melanoma metastasis by activating JNK." (PMID 26808375, 2016). "It was not clear which of these pathways mediates FZD7 function during melanoma metastasis." (PMID 26808375, 2016). "Knocking down of FZD7 did not reduce the number of metastases from either MA-2 or MeWo cells 24 hrs after injections, indicating that FZD7 is not required for the seeding and initial survival of melanoma cells in lung." (PMID 26808375, 2016).
melanoma (continued). "Interestingly, treatment of MA-2 human melanoma cells with WNT3 or LiCl increased canonical WNT signalling, and decreased JNK (non-canonical Wnt signalling) in cells with FZD7 knockdown, suggesting that FZD7 suppresses the canonical Wnt pathway in melanoma cells." (PMID 27196929, 2016). "We found that ANXA1, FZD7 and PTGR1 were MITF direct targets in CL1-0 cells, but these genes were not regulated in melanoma 501MEL cells." (PMID 33293474, 2020).
glioma (13 papers, 2016 to 2025). A benign or malignant brain and spinal cord tumor that arises from glial cells (astrocytes, oligodendrocytes, ependymal cells). "FZD7, linked to glioma cell motility and invasiveness, aligns with our observation of TGIF2 promoting glioma cell migration." (PMID 38629068, 2024). "In this study, we detected high-level FZD7 expression in glioma and its overexpression was associated with advanced tumor stage." (PMID 27852064, 2016). "To study the underlying molecular mechanisms by which FZD7 promotes proliferation of glioma cells, we analyzed the downstream targets of FZD7." (PMID 27852064, 2016). "In glioma, patient sample studies were shown to overexpress Fzd7, and both in vitro and in vivo interrogation revealed miR-206 targets Fzd7 while also decreasing cell proliferation, migration, and invasion." (PMID 34671643, 2021). "FZD7 promoted glioma cell proliferation by upregulation of Tafazzin (TAZ) via the β-catenin/TCF-mediated transcription in glioma cells." (PMID 29789460, 2018). "The expressions of FZD7, along with other two genes, SFRP1 and SFRP4, were identified to be associated with poor prognosis in glioma patients." (PMID 29050331, 2017). "Taken together, these results suggest that TAZ is essential for FZD7-induced glioma cell proliferation." (PMID 27852064, 2016). "To evaluate the functional role of FZD7 in glioma, we examined the effect of FZD7 overexpression on the proliferation of U-87MG and U-251MG cells." (PMID 27852064, 2016). "Collectively, these results suggest that glioma patients with high FZD7 expression have a poor overall survival." (PMID 27852064, 2016). "Our study demonstrates that FZD7 is overexpressed in glioma, and its overexpression contributes to glioma tumorigenesis by upregulating TAZ." (PMID 27852064, 2016). "The results show, furthermore, that high FZD7 expression indicates a poor prognosis in glioma patients." (PMID 27852064, 2016). "Our study not only yields a better understanding of the role of FZD7 in glioma, but also paves the way for novel and powerful anticancer therapeutics." (PMID 27852064, 2016). "In this study, we show that expression of FZD7 is significantly higher in tumor tissue than that in the adjacent non-tumor tissues, and upregulated FZD is associated with advanced tumor stage in glioma." (PMID 27852064, 2016). "To conclude, our study demonstrates that FZD7 is overexpressed in glioma, which leads to increased cell proliferation through upregulation of TAZ." (PMID 27852064, 2016). "In this study, high FZD7 expression was detected in glioma, and its overexpression promoted glioma cell proliferation in vitro and in vivo." (PMID 27852064, 2016). "In vitro functional assays showed that forced overexpression of FZD7 promoted proliferation of gliomas cells, whereas knockdown of endogenous FZD7 significantly suppressed proliferation ability of these cells." (PMID 27852064, 2016). "In glioma, FZD7 is upregulated, correlating with poor patient outcomes." (PMID 41031155, 2025). "Fzd7 acted as a miR-638 regulating factors, could be regulated by hsa-circ-0000177, and finally stimulated the Wnt signaling pathway to regulate glioma growth." (PMID 35492076, 2022). "To further test whether FZD7 is required for the proliferation of glioma cells, we silenced FZD7 in glioma cells using lentivirus-mediated shRNA interference." (PMID 27852064, 2016). "About 70% (28 of 40) of high-grade gliomas (grades III & IV) were found to overexpress FZD7." (PMID 27852064, 2016). "Furthermore, the univariate analysis of survival shows that glioma patients with high FZD7 expression have a shorter survival." (PMID 27852064, 2016). "Furthermore, we tested the correlation of FZD7 expression with Ki67, a cellular marker for proliferation, in glioma patients." (PMID 27852064, 2016). "In addition, the correlation between expression pattern of FZD7 in glioma and their clinicopathological characteristics was also studied." (PMID 27852064, 2016).
glioma (continued). "We further found that FZD7 could activate transcriptional coactivator with PDZ-binding motif (TAZ), and TAZ was required for FZD7 to promote cell proliferation in glioma." (PMID 27852064, 2016). "In conclusion, our findings demonstrate that FZD7 may promote glioma cell proliferation via upregulation of TAZ." (PMID 27852064, 2016). "Taken together, these results indicated that FZD7 promoted glioma cell proliferation in vitro." (PMID 27852064, 2016). "In addition, univariate analysis of survival indicates that glioma patients with high FZD7 expression have a poor overall survival." (PMID 27852064, 2016). "To investigate the role of FZD7 in glioma development, we tested the expression of FZD7 in glioma." (PMID 27852064, 2016). "The up-regulated expression of FZD7 could promote glioma cell proliferation." (PMID 29050331, 2017). "However, the role of FZD7 in the development of glioma remains largely unexplored." (PMID 27852064, 2016). "Therefore, targeted inhibition of FZD7 may represent a novel and promising therapeutic approach for glioma, especially the advanced stage of glioma." (PMID 27852064, 2016). "Fzd7 expression is increased in CRC due to circ_CSPP1 sponging miR-944 and in glioma due to circ_0000177 sequestering miR-638." (PMID 34671643, 2021). "Therefore, we hypothesized that FZD7 might activate TAZ in glioma cells." (PMID 27852064, 2016). "To further confirm these findings, we examined the expression of FZD7 and TAZ in five other independent glioma microarray datasets." (PMID 27852064, 2016). "Although this has not been demonstrated in brain cancer, YAP and TAZ are frequently upregulated in glioma, and studies have shown that TAZ is required for the FZD7-induced proliferation of glioma cells, while TAZ inhibition leads to senescence and growth arrest." (PMID 32575464, 2020). "Moreover, immunohistochemisty analysis of the expression patterns of FZD7 and TAZ in glioma samples demonstrated a significant correlation between them." (PMID 27852064, 2016). "To determine whether FZD7 promotes proliferation of glioma cells through upregulation of TAZ, we knocked down the endogenous TAZ in U-87MG cells overexpressing FZD7." (PMID 27852064, 2016). "We further examined the FZD7 expression in 76 glioma tissues and its adjacent non-tumor tissues using immunohistochemisty." (PMID 27852064, 2016). "In the present study, our data suggest that FZD7 promotes glioma cell proliferation via upregulation of TAZ, and FZD7 may enhance the expression of TAZ through β-catenin/TCF-mediated transcription in glioma cells, which is consistent with the oncogenic role of TAZ in glioma previously reported." (PMID 27852064, 2016). "To summarize, our data suggested that FZD7 could upregulate and activate TAZ in glioma cells." (PMID 27852064, 2016). "However, the role of FZD7 in the development and progression of glioma is still not fully understood." (PMID 27852064, 2016). "Furthermore, FZD7 directly regulated the expression of transcriptional coactivator with PDZ-binding motif (TAZ) (also known as WW domain containing transcription regulator 1, WWTR1) in glioma cells, suggesting that FZD7 may promote glioma cell proliferation via upregulation of TAZ." (PMID 27852064, 2016).
glioblastoma (12 papers, 2016 to 2022). The most malignant astrocytic tumor (WHO grade IV). "The miR-504 hindered the mesenchymal phenotype of glioblastoma through downregulating FZD7 and impacting E-cadherin/β-catenin." (PMID 36170021, 2022). "A decreased expression ratio of the miRNA miR-504/FZD7 was shown to be a potential molecular marker for identifying the mesenchymal subtype in glioblastoma." (PMID 35205289, 2022). "Liu et al47 demonstrated that miR‐504 suppresses the EMT process of glioblastoma via targeting the FZD7‐mediated Wnt/β‐catenin pathway." (PMID 33026174, 2020). "Kaplan–Meier analysis revealed that glioblastoma patients with high expression of FZD7 had a worse overall survival probability (p = 4.8E-04)." (PMID 27852064, 2016). "In addition to these miRNAs, miR-182-targeted MTSS1 enhanced TGF-β1-related EMT in gliomas, and miR-504 inhibited EMT in glioblastomas by targeting the Wnt receptor FZD7/β-catenin pathway." (PMID 35205289, 2022). "Likewise, high level of FZD7 also conferred poor prognosis for glioblastoma patients in the GSE16011 dataset (p = 4.0E-12)." (PMID 27852064, 2016). "Also, in glioblastoma, Fzd7 is expressed inversely to miR-504." (PMID 34671643, 2021). "In glioblastoma, miR-144-3p binds to the 3′UTR of Fzd7 and inhibits proliferation, invasion, and migration." (PMID 34671643, 2021).
intrahepatic cholangiocarcinoma (12 papers, 2021 to 2025). A carcinoma that arises from the intrahepatic bile duct epithelium in any site of the intrahepatic biliary tree. "These include FZD7 (Frizzled Class Receptor 7) in intrahepatic cholangiocarcinoma, Tumor-Associated Epithelial Mucin in lung adenocarcinoma, and FOXK1 (Forkhead Box K1) and CTP Synthase 1 in triple-negative breast cancer." (PMID 38255791, 2024). "CircACTN4 has been demonstrated to interact with YBX1 to activate FZD7 transcription, thereby promoting intrahepatic cholangiocarcinoma progression." (PMID 36895010, 2023). "CircACTN4 can recruit YBX1 to the promoter of FZD7 and activate its transcription in human intrahepatic cholangiocarcinoma cells." (PMID 37907737, 2023). "CircACTN4 promotes intrahepatic cholangiocarcinoma proliferation and metastasis by acting as a sponge for miR-424-5p and by interacting with YBX1 to transcriptionally activate FZD7, which is upregulated in intrahepatic cholangiocarcinoma expression." (PMID 36506086, 2022). "Similarly, circACTN4 facilitates Y-box binding protein 1 (YBX1) recruitment to activate FZD7 transcription and then activates the Wnt and Hippo signalling pathways, thereby promoting intrahepatic cholangiocarcinoma (ICC) growth and metastasis." (PMID 40296024, 2025). "Likewise, in intrahepatic cholangiocarcinoma, circACTN4 also interacts with YB-1 and co-initiates the transcription of the downstream target FZD7, promoting the progression of intrahepatic cholangiocarcinoma." (PMID 35406781, 2022). "Circ-ACTN4 binds YBX1 and stimulates FZD7 transcription, which in turn promotes intrahepatic cholangiocarcinoma (ICC) proliferation and metastasis, leading to malignant tumor growth and metastasis." (PMID 35116058, 2021). "For instance, CircACTN4 was demonstrated to be upregulated in ICC (intrahepatic cholangiocarcinoma) patients, acting as a molecular sponge of miR-424-5p and interacting with YBX1, to transcriptionally activate FZD7, thereby promoting proliferation and metastasis of ICC." (PMID 36304901, 2022). "In our previous study, circACTN4 promoted intrahepatic cholangiocarcinoma proliferation and metastasis by acting as a molecular sponge of miR-424-5p and interacting with YBX1 to transcriptionally activate FZD7." (PMID 36028854, 2022). "For instance, circACTN4 functions as a sponge to eliminate miR-424-5p to upregulate and recruit Yes-associated protein 1 (YAP1), which exerts a positive effect on inducing Frizzled-7 (FZD7) and in turn facilitates the development of intrahepatic cholangiocarcinoma." (PMID 36875073, 2023). "Another study indicated that circACTN4 is upregulated in intrahepatic cholangiocarcinoma by acting as a molecular sponge for miR-424-5p and interacting with YBX1 to transcriptionally activate FZD7, thereby promoting the proliferation and metastasis of intrahepatic cholangiocarcinoma." (PMID 36505874, 2022).